SLC9A3-OT1 (SLC9A3 3' UTR overlapping transcript 1)
Synonyms: PP7080
Gene: Long non-coding RNA gene on chromosome 5 (466,124 to 473,098, reverse strand). Ensembl gene ENSG00000188242.
Diseases named in the same sentence as SLC9A3-OT1 in open-access papers:
SLC9A3-OT1 is named in the same sentence as 3 diseases in open-access papers, as found by Europe PMC text mining. Sharing a sentence is not in itself a finding about the gene and the disease.
SLC9A3-OT1 shares sentences with these, for which no sentence is quoted: asthma (1 paper); cancer (1); cervical cancer (1).